SUDS3 (SIN3A corepressor complex component SDS3)
Description:
Regulatory protein which represses transcription and augments histone deacetylase activity of HDAC1. May have a potential role in tumor suppressor pathways through regulation of apoptosis. May function in the assembly and/or enzymatic activity of the mSin3A corepressor complex or in mediating interactions between the complex and other regulatory complexes.
Synonyms: SAP45; SDS3; FLJ00052
Tractability: PROTAC: UniProt records ubiquitination sites on it; ubiquitination databases record sites on it; its protein half-life has been measured.
Gene: Protein-coding gene on chromosome 12 (118,376,531 to 118,418,033, forward strand). Ensembl gene ENSG00000111707.
Subcellular location: Nucleus
Subcellular location (Human Protein Atlas): Cytosol; Nuclear bodies
Pathways (Reactome):
Chromatin organization: HDACs deacetylate histones
Disease: Potential therapeutics for SARS
Gene expression (Transcription): NoRC negatively regulates rRNA expression
Metabolism of proteins: Ub-specific processing proteases
Gene Ontology:
Molecular function: enzyme binding; histone deacetylase activity; protein binding; histone deacetylase binding; identical protein binding
Biological process: chromatin remodeling; negative regulation of transcription by RNA polymerase II; substantia nigra development; negative regulation of cell migration; negative regulation of DNA-templated transcription; negative regulation of stem cell population maintenance; negative regulation of transforming growth factor beta receptor signaling pathway; positive regulation of stem cell population maintenance
Cellular component: nuclear body; nucleus; nucleoplasm; Sin3-type complex
Genetic constraint (gnomAD): Loss-of-function variants: 21 observed, 41.32 expected, observed/expected ratio (o/e) 0.51, 90% interval 0.36 to 0.73. The upper end of that interval is the gene's LOEUF score, 0.73, which puts it in group 2 of 6, group 1 being the genes least tolerant of losing a copy. Missense variants: 266 observed, 332.56 expected, observed/expected ratio (o/e) 0.8, 90% interval 0.72 to 0.88. Synonymous variants: 141 observed, 124.74 expected, observed/expected ratio (o/e) 1.13, 90% interval 0.99 to 1.3.
Homologues: Orthologues: chimpanzee SUDS3 (100% identical), macaque SUDS3 (100% identical), dog SUDS3 (98% identical), rat Suds3 (98% identical), guinea pig SUDS3 (98% identical), rabbit SUDS3 (97% identical), mouse Suds3 (97% identical), pig SUDS3 (96% identical), zebrafish suds3 (84% identical), tropical clawed frog suds3 (84% identical), Drosophila melanogaster CG14220 (40% identical). Paralogues in human: BRMS1L (27% identical), BRMS1 (18% identical).
Diseases named in the same sentence as SUDS3 in open-access papers:
SUDS3 is named in the same sentence as 6 diseases in open-access papers, as found by Europe PMC text mining. Sharing a sentence is not in itself a finding about the gene and the disease. The quoted sentences say what the papers report.
breast tumors (1 paper, 2023). "SIN3B, HDAC1, HDAC2, SUDS3, and RBBP4, but not SIN3A and SAP18, were also upregulated to a lesser degree in human breast tumors." (PMID 37655663, 2023).
tumor (4 papers, 2012 to 2020). "Subsequently, we identified that SUDS3, a tumor-facilitator with elevated expression in TNBC, was the downstream target of SNHG22/miR-324-3p axis." (PMID 32565736, 2020). "Based on these results, we selected SUDS3, a tumor-promoter in TNBC, as the downstream of SNHG22/miR-324-3p axis." (PMID 32565736, 2020). "Of note, miR-324-3p repression or SUDS3 overexpression could rescue the anti-tumor effect of SNHG22 silencing on the malignant phenotypes of TNBC cells." (PMID 32565736, 2020).
SUDS3 also shares sentences with these, for which no sentence is quoted: cancer (3 papers); amyotrophic lateral sclerosis (1); metastatic tumor (1); triple-negative breast carcinoma (1).